USF1 (upstream transcription factor 1)
Diseases named in the same sentence as USF1 in open-access papers (continued):
Sharing a sentence is not in itself a finding about the gene and the disease.
cancer (32 papers, 2009 to 2025). A tumor composed of atypical neoplastic, often pleomorphic cells that invade other tissues. "There were also associations unique to each cancer type, including USF1 and SMAD1 for BRCA, FOXF2 for HNSC, and NFE2L2 and NR3C1 for UCEC." (PMID 28139702, 2017). "Accordingly, a loss of transcriptional activity of USF1 in many cancer cell lines was observed (discussed in Corre and Galibert)." (PMID 26068452, 2015). "Since USF-1 mediates an independent and crucial DNA-repair program as highlighted by our USF-1 KO and KD assays, we propose that impairment of this pathway will promote genome instability in response to environmental insults, which is a hallmark of cancer." (PMID 22291606, 2012). "USF1 and USF2 were among the first mammalian transcription factors identified and have long been linked to cancer." (PMID 40658711, 2025). "Other KDs were associated with signal transduction and kinase activity (PRKCA, TAOK1, and ADRBK1), membrane transport (SLC9A3R1), metabolism (PPP1R3B), gene regulation (USF1), and immune responses and cancer (SLAMF8, SRC, and KIAA0100)." (PMID 41402937, 2025). "Subsequently, the CNV of 27 genes in pan-cancer samples were also analyzed, and it was found that USF1 had a high amplification rate and a low deletion rate." (PMID 41008813, 2025). "Our study found that, in cancer cells, DUSP18 affects cancer progression through its influence on USF1-SREBP2-driven transcriptional cascade that increases micro-environmental lanosterol and blocks CD8+ T cell activation." (PMID 38992029, 2024). "To date, the implication of USF1 in cancer development has been investigated through only one angle, its function as a transcription factor." (PMID 24831529, 2014). "Moreover, in cancer cell lines, RAD51 is associated with the regulation of the autophagy pathway and works together with E-box proteins such as USF1, USF2, and MITF to regulate the expression of autophagy-related genes." (PMID 40746357, 2025). "ARHGEF7 plays a role in cytoskeleton remodeling, and may regulate cancer cell motility, USF1 expression is related to cellular stress and senescence, immune response and carcinogenesis and has been shown to be associated with shorter life expectancy." (PMID 32751422, 2020). "Functional USF1 TFBSs showed a depletion of substitutions compared to flanking regions—in the 1KG polymorphism as well as the cancer dataset—but this depletion was absent at control sites." (PMID 27490693, 2016). "Therefore, we speculate that ERK5 might contribute to cancer metastasis by regulating the TGF-β1-mediated EMT process through USF1, which deserves further investigation in detail." (PMID 32144580, 2020). "In addition, the phosphorylation level of USF1 paralleled ERK5 activity and was found to be enhanced in highly metastatic B16F10 and 95D cancer cells, suggesting the involvement of USF1 in ERK5-regulated FAK expression and subsequent cell metastasis and invasion." (PMID 32144580, 2020). "In addition, USF1 has been found to regulate the development of various cancers, but whether it can regulate the transcription of HAS2-AS1 remains unclear." (PMID 32776110, 2020). "The module USF1 has a high intersection with the COAD; however, its boundary neighbors also have a tight coverage with cancer-related genes (coverage = 0.84)." (PMID 32193399, 2020). "In summary, we revealed that candidate transcription factors identified from the CRISPR/Cas9 screen including USF2 and USF1, regulate HOXA9 thereby providing a more comprehensive understanding about how the HOXA9 locus is regulated in human cancer cells." (PMID 33001025, 2020).
cancer (continued). "Analyzing the clinical cancer and normal samples from the mouth has shown that the level of expression of USF1 and USF2 is lower in the cancer samples, but the hTERT expression and telomerase activity is higher in the cancer samples." (PMID 22649586, 2009). "Notably, the transcription factor USF1 was identified as a regulator of CTU2 expression and has been confirmed to be an oncogene widely expressed in multiple cancer types." (PMID 40375999, 2025). "Mechanically, DUSP18 increases the activity of the USF1-SREBP2 transcription factor (TF) axis, upregulates the cholesterol biosynthetic pathway and allows for the accumulation of lanosterol, a cholesterol precursor, in cancer cells." (PMID 38992029, 2024). "Furthermore, USF1 transcriptionally elevated FAK expression by directly binding to its promoter, thereby promoting cancer metastasis and invasion." (PMID 32144580, 2020). "As a result, we speculated that tobacco smoke might induce cancer by targeting genes such as MAX and USF1." (PMID 26629988, 2015). "In addition, in cancer cells, there was a strong tendency of co-occurrence between high LGALS3BP, high USF1, high USF2, and high TGF-β1 expression (p < 0.001) or low LGALS3BP, low USF1, low USF2, and low TGF-β1 expression (p < 0.001)." (PMID 33888686, 2021). "IGF1R, one of the members of the insulin/IGF system, was mostly expressed in foetal and cancer tissues 39 and three CpG islands are predicted in the promoter region of IGF1R which may combine large list of transcript factors including MZF1, TCFL5, USF1, ETS1 and SPIB." (PMID 33085184, 2020).
tumor (30 papers, 2013 to 2026). "We next explored the tumor immunological association of USF1." (PMID 37900187, 2023). "Thus, superenhancer‐associated FASRL expression driven by USF1 promoted tumor progression through the interaction between FASRL and ACACA to increase FA synthesis." (PMID 36307901, 2022). "We therefore investigated whether loss of USF1 favors tumor growth in vivo under stress conditions." (PMID 24831529, 2014). "Mechanistically, MIR4435-2HG directly interacts with USF1 and promotes its protein stability by facilitating USF1 succinylation, thereby enhancing tumor cell migration and invasion through the induction of epithelial - mesenchymal transition." (PMID 42132011, 2026). "Taken together, our observations have revealed a crucial role for DUSP18/USF1/SREBF2-lanosterol signaling in tumor immunosuppressive reprogramming." (PMID 38992029, 2024). "Previous research has demonstrated that aberrant expression of USF1 can initiate tumour formation and facilitate the progression of tumours." (PMID 37665075, 2023). "This factor and its family member USF1 have been well characterized for their role in cell cycle regulation and tumor suppression, with both pro- and antiproliferative roles reported across cell types." (PMID 37097016, 2023). "By analyzing TCGA database, USF1 was highly expressed in LUAD and its expression was associated with clinical pathologic characteristics of patients with LUAD, including tumor stage, nodal metastases, and poor survival rate." (PMID 35155573, 2022). "The knockdown of USF1 inhibited cells viability, proliferation, migration and invasion, and reduced the tumor volume." (PMID 35155573, 2022). "The expression changes of USF1 in tumor tissues following shRNA injection were confirmed by Western blotting analysis." (PMID 35155573, 2022). "Thirty days later, tumor size in mice treated with USF1 shRNA was smaller than that in NC group of mice." (PMID 35155573, 2022). "In line with this, tumor volume and weight of mice in USF1 shRNA group were lower than those in NC group (p < .05)." (PMID 35155573, 2022). "UALCAN's gene expression dataset (ualcan.path.uab.edu) showed that the expression of USF1 in tumor tissues was significantly higher relative to normal tissues." (PMID 34766130, 2020). "It was found that the expression of USF1 in the tumor group was significantly up-regulated and positively correlated with the expression of HAS2-AS1." (PMID 32776110, 2020). "To this end, we used bioinformatics to explore the upstream transcription factors of HAS2-AS1, and found that the expression of USF1 in the tumor group was significantly up-regulated and positively correlated with the expression of HAS2-AS1." (PMID 32776110, 2020). "The findings revealed that USF1 was strongly expressed in Huh7 cells and tumor tissues of HCC relative to their respective controls." (PMID 34766130, 2020). "Knockdown of ZFAS1 significantly suppressed tumour proliferation, migration, invasion and USF1 expression." (PMID 31565837, 2019). "Other candidates such as EGR1, RUNX2, STAT1, TRAP2, IRF1 and USF1 have been experimentally validated as drug targets, metastasis promoter or tumor growth enhancers, see19–24." (PMID 31857653, 2019). "The effects of ZFAS1, miR‐296‐5p and USF1 on tumour growth were further confirmed using xenograft model." (PMID 31565837, 2019). "HPSE and USF1 staining were predominantly in the nuclei, and the positive signal was brown-yellow granules in tumor cell nuclei." (PMID 25149140, 2014). "Notably, we also found a USF1-downstream gene PTBP1, which had been linked to the immune evasion of tumor cell in TNBC." (PMID 37900187, 2023).
tumor (continued). "As UGT1A3 was closely related to tumor drug resistance, discovery of transcriptional relationship between USF1 and UGT1A3 may provide a new idea for the study of drug resistance and therapy, and USF1 could serve as a potential therapeutic target for LUAD." (PMID 35155573, 2022). "As compared with adjacent normal tissues, USF1 was highly expressed in tumor tissues." (PMID 35155573, 2022). "USF1 expression in HCC tumor tissues, Huh7, and L02 cells was measured by Western blotting." (PMID 34766130, 2020). "Knockdown of USF1 inhibited cell proliferation and metastasis and xenograft tumour growth." (PMID 31565837, 2019). "In that case, we conducted experiments not only in vitro but also in vivo and found ZFAS1/miR‐296‐5p/USF1 regulation might work as one approach to influence tumour progression." (PMID 31565837, 2019). "In addition, RT‐qPCR analysis demonstrated that knockdown of LOXL1‐AS1 contributed to the decrease of LOXL1‐AS1 and USF1 expression and the enhancement of miR‐708‐5p level in neoplasms from mice." (PMID 31468594, 2019). "Moreover, we found both USF1 and PTBP1 expression were significantly associated with the infiltration levels of CD4+ Th1 cells that could function in pro-tumor immunity." (PMID 37900187, 2023). "Finally, we report that knocking down USF-1 decreases tumor cell migration." (PMID 29871931, 2018). "In turn, USF1 induces the SREBF2 gene, which allows cells to accumulate the cholesterol biosynthesis intermediate lanosterol and release it into the tumor microenvironment (TME)." (PMID 38992029, 2024). "For the upstream analysis, we found that USF1 directly binds to the ATRAP promoter to activate its expression, which further participated in tumor malignant transforming processes." (PMID 35414770, 2022). "In conclusion, the results of the present study on the effect of TGF-β1 on 90K transcription and the role of USF1 and USF2 in the regulation of 90K gene expression have uncovered a novel possible role for 90K in the TGF-β1-driven tumor progression program." (PMID 33888686, 2021). "The data demonstrated that only USF1, YY1, STAT3 and USF2 were up-regulated in the three OS tumor samples when compared with paired normal specimens." (PMID 32269179, 2020). "USF-1 is involved in the transcriptional activation of PTEN and Src-suppressed C kinase substrate (SSeCKS), two different tumor suppressor genes." (PMID 31337730, 2019). "The top TFs found to negatively regulate the expression of cell cycle genes (SMAD5, IKZF1, USF1, USF2) have been previously shown to have a role as transcriptional repressors and as inhibitors of cellular proliferation in tumor cell lines." (PMID 28899340, 2017). "Both USF1 and USF2 are supposed to have major roles in metabolism, tissue protection and tumor development." (PMID 25741280, 2015). "USF1 and USF2 were also found to be up-regulated in primary HCC tumor tissues (all P < 0.001, respectively)." (PMID 25149140, 2014). "This suggests that USF1 and potentially other CRC TFs may contribute to immune modulation in TNBC, which has implications for understanding the tumor microenvironment and potential immunotherapeutic strategies in TNBC." (PMID 37900187, 2023). "Importantly, in tumor samples, the expression levels of LGALS3BP showed a direct correlation with those of TGF-β1 (R = 0.34, p < 0.001), USF1 (R = 0.30, p < 0.001), and USF2 (R = 0.37, p < 0.001)." (PMID 33888686, 2021). "Correlation analysis disclosed the positive association between USF1 and LOXL1‐AS1 as well as the negative correlation between USF1 and miR‐708‐5p in clinical tumour tissues." (PMID 31468594, 2019).
cardiovascular disease (6 papers, 2013 to 2025). "Risk alleles of USF1 have been found to be associated with cardiovascular disease and type 2 DM risk in a number of studies." (PMID 35213968, 2022). "Upstream transcription factor 1 (USF1) allelic variants significantly influence future risk of cardiovascular disease and overall mortality in females." (PMID 24722012, 2014). "Importantly, USF1 has also emerged as an interesting therapeutic target in the context of metabolic and cardiovascular disease." (PMID 34385562, 2021).
infection (5 papers, 2017 to 2023). The state of being infected such as from the introduction of a foreign agent such as serum, vaccine, antigenic substance or organism. "EMSA and DNA pull-down assay showed that BMDC infection with LDPm induced Ets1, Ets2, USF1, and USF2 binding to the mouse HAVCR2 promoter." (PMID 37202419, 2023). "To further examine the role of USF for regulating latency, we monitored the proportion of productively infected cells for three weeks following infection of wildtype, USF1 KO, and USF2 KO cells." (PMID 37515158, 2023). "Similar to the results with unsorted infected cells, we found that the WT, USF1, and USF2 deficient cells produced a nearly equivalent proportion of productively infected cells at 3 and 4 days post-infection." (PMID 37515158, 2023). "HCV reduced the expression level of USF-1 in a time-dependent manner up to 72 h after infection, the study endpoint." (PMID 31337730, 2019). "Our results have also shown that TIM-3 expression is upregulated on DCs following LD infection and that LD mediates this effect by activating a TIM-3 signaling pathway Btk→STAT3→IL-10→c-Src→Ets1/2, USF1/2." (PMID 37202419, 2023). "We found that infection of the USF1 knockout cells produced a small but not significant decrease in RGH or HIVGKO infectivity compared to the wildtype, as determined 4 days post-infection." (PMID 37515158, 2023).
USF1 also shares sentences with these, for which no sentence is quoted: Insulin resistance (6 papers); type 2 diabetes (3); cervical cancer (2); hepatoblastoma (2); Hypercholesterolemia (2); Iron deficiency (2); neuroblastoma (2); skin carcinoma (2); Stroke (2); adenocarcinoma (1); Arthritis (1); autism (1); bacterial infection (1); bladder cancer (1); calcium kidney stones (1); COVID-19 (1); Cowden syndrome (1); dyslipidaemia (1); follicular thyroid carcinoma (1); glioblastoma (1); Hepatitis B (1); Hepatitis C (1); Hyperinsulinemia (1); hypovitaminosis D (1); Kidney Degeneration (1); lipid metabolism disorders (1); Lipid storage disease (1); lung squamous cell carcinoma (1); lymph node metastasis (1); ovarian carcinoma (1).
A further 4 diseases each share a sentence with USF1 in 1 paper.